TLR9 (toll like receptor 9)
Diseases named in the same sentence as TLR9 in open-access papers (continued):
Sharing a sentence is not in itself a finding about the gene and the disease.
tumor (continued). "When activated, TLR7 and TLR9 on pDCs can secrete large amounts of IFN-I, which can both inhibit the proliferation of tumor cells and activate the immune system to exert anti-tumor effects." (PMID 37876967, 2023). "In a mouse model of anti-tumor immunity, the TLR9 agonist CpG has been shown to enhance the CD8 T cell response in vitro, in a B cell and contact-dependent manner, resulting in an improved tumor growth control and a higher mouse survival." (PMID 36969196, 2023). "Mechanistically, NETs directly upregulated the TLR9 pathway in DLBCL and subsequently triggered the NF-κB, STAT3, and p38 pathways to promote tumor progression." (PMID 35747797, 2022). "Another study on the immune microenvironment of GC indicated close relationships among the expression of ICOS in Foxp3+ tumor-infiltrating lymphocytes and pDCs, the expression of ICOS-L and TLR9 of pDCs, and H. pylori infection." (PMID 35311157, 2022). "Specifically, the tumors are able to inhibit TLR-9; thus, although plasmacytoid DC enter the TME, their ability to promote anti-tumor responses inside the tumor is compromised." (PMID 36143308, 2022). "By combining a TLR9 agonist and an agonistic antibody against OX40 with anti-PD-L1, mice experience tumor regression and are protected from new TNBC tumor outgrowth." (PMID 35760778, 2022). "Activation of pattern recognition receptor pathways, such as toll-like receptor 9 (TLR9), leads to the local production of interferons in the tumor microenvironment." (PMID 35760778, 2022). "Nevertheless, direct contact between myeloma cells and pDCs would degrade TLR9 of pDCs, which greatly reduced IFN-α expression, and promoted tumor progression." (PMID 36618371, 2022). "First is the recruitment phase of DCs, where cytokines, Toll-like receptor (TLR)-9 agonists, and STING agonists will induce local IFN-γ release, leading to the recruitment and activation of DCs in the tumor area." (PMID 36713427, 2022). "We previously reported that macrophages treated with a TLR9 agonist in combination with an anti-PD1 antibody acquired a phenotype characterized by immunosuppressive and pro-tumor activity, as demonstrated in vivo and in vitro." (PMID 36555441, 2022). "The immunoregulatory CpG was further applied to activate TLR9, thus maintaining immunostimulation by increased expression of heat shock protein 70 (HSP70) and continuous exposure of tumor antigens." (PMID 35910806, 2022). "TLR9−/− mice treated intratumorally with FITC-labeled E7 peptide and chemotherapy had significantly less FITC+ DCs in the tumor draining lymph nodes." (PMID 35626062, 2022). "TLR9 can promote metastasis, with evidence that the agonist CpG ODN promotes and enhances tumor progression and proliferation." (PMID 36389785, 2022). "On the contrary, the hypermethylated DNA, TLR9 inhibitor, and HGFR inhibitor co-administration increased the tumor cell proliferation." (PMID 36359370, 2022). "Among patients undergoing upfront surgery, stage, perivascular invasion, tumor differentiation grade 3, a high expression of TLR7, and a high expression of cytoplasmic TLR9 emerged as prognostic markers in univariate analysis." (PMID 35536778, 2022). "TLR9 agonists contribute to remodeling of the lung TME, leading to the formation of tertiary lymphoid structures near the tumor, CD8+ T-cell infiltration of the tumor, DC expansion, and antibody production." (PMID 36365103, 2022). "A combined administration of TLR7 and TLR9 agonists with PD-1 blockade in head and NSCC suppresses tumor growth with an abscopal effect observed related to TAM and CD8+ T cells activation." (PMID 36230990, 2022). "Studies have shown that TLR9 agonists enhance radiofrequency ablation-induced CTL (cytotoxic T lymphocyte) response, effectively inhibiting tumor growth and lung metastasis." (PMID 36248807, 2022). "Preclinical murine data demonstrated that class C TLR9 agonist delivered via PV reduced LM burden, possibly by altering the TME and enabling anti-tumor immunity." (PMID 35697801, 2022).
tumor (continued). "Inosine activation of the A2AR on T cells is itself complex: inosine either prevented Th1 differentiation and blunted anti-tumor immunity in anti-CTLA4-treated mice or, conversely, enhanced both, when co-supplied with IFNγ in vitro and a TLR9 agonist in vivo." (PMID 34986329, 2022). "NET-HMGB1 interacts with the TLR9 of tumor cells and then stimulates TLR9 signaling which subsequently activates p38 and JNK pathways for tumor proliferation, adhesion, migration, and invasion." (PMID 34868992, 2021). "HCC cells show increased proliferation under the stimulation of TLR9, whereas inhibition of TLR9 using HCQ results in the reduction of HCC proliferation and tumor growth both in vitro and in vivo." (PMID 34203465, 2021). "Activation of TLR9 upregulates NF-κB and MAPK signaling, leading to NO production, which is a key factor to increase the radiosensitivity of tumor through induction of apoptosis." (PMID 34715891, 2021). "We evaluate BCG intratumoral treatment in a subcutaneous MB49 tumor model using different knockout (KO) mice (STING−/−, cGAS−/−, TLR2−/−, TLR3−/−, TLR4−/−, TLR7−/−, TLR9−/−, TLR3/7/9−/−, MyD88−/−, IL-1R−/−, Caspase1/11−/−, Gasdermin-D−/− and IFNAR−/−)." (PMID 34341449, 2021). "Established tumor regression occurred with the further addition of innate immune cell activators anti-CD40 and TLR9 agonist." (PMID 33803078, 2021). "The Toll-like receptor 9 agonist CpG increased anti-tumor T cell responses following RFA and prolonged survival and reduced new tumor growth." (PMID 34575463, 2021). "During tumor development, a variety of growth factors including insulin growth factor 1 (IGF1) have been shown to activate the TLR-9 signaling pathway and promote cancer progression by increasing the cell proliferation and inhibiting apoptosis." (PMID 34439380, 2021). "Herein, we investigate the effect of BCG tumor treatment in TLR2−/−, TLR4−/−, TLR7−/− and TLR9−/− mice." (PMID 34341449, 2021). "NETs can directly increase TLR9 expression in DLBCL and promote tumor progression via the NF-κB, signal transducer and activator of transcription 3 (STAT3) and p38 pathways." (PMID 34758877, 2021). "A synergy of HMGB1 and TLR9 was shown to up-regulate mitochondrial biogenesis of HCC cell lines and in murine HCC models under hypoxic conditions, promoting tumor survival and proliferation." (PMID 34025657, 2021). "DaRT used in combination with the TLR9 agonist CpG, TLR3 agonist, poly I:C, or with the TLR1/2 agonist XS15, retarded tumor growth and increased tumor-rejection rates, compared with DaRT alone." (PMID 33503958, 2021). "HCC cells exhibit increased proliferation under the stimulation of TLR9, whereas the inhibition of TLR9 using HCQ results in the decrease of HCC proliferation and tumor growth both in vitro and in vivo." (PMID 34203465, 2021). "Specifically, TLR9 promoted PD-L1 transcriptional expression by enhancing STAT3 Tyr705 phosphorylation, resulting in tumor cell immune escape." (PMID 32483468, 2020). "Upon TLR9 activation, STAT3 phosphorylation at Tyr705 was increased, which led to PD-L1 expression upregulation in HCC cells, suggesting that tumor cells can be directly affected by TLR9 ligation to escape immune attack." (PMID 32483468, 2020). "As observed with TLR9 agonists, attempts to improve the retention of TLR7/8 agonists in the tumour by formulating resiquimod into thermosensitive liposomes have been investigated." (PMID 33352882, 2020). "For example, CpG oligodeoxynucleotides that mimic bacterial DNA acts as a PAMP to trigger a TLR9-dependent TLR4 activation and tumor necrosis factor (TNF)-α production by tumor-infiltrating myeloid-derived cells." (PMID 32817793, 2020). "Since TLR9 is predominantly expressed in DCs, CpG-ODN, as an agonist of TLR9, induce Th1 and tumor-specific CTLs via endosome uptake and maturation of DCs as well as the secretion of IL-12 cytokine." (PMID 32952954, 2020).
tumor (continued). "This same group also tested this vaccine with PD-1 blockade combined with either CD137 or toll like receptor-9 (TLR-9) agonists and observed 75% tumor rejection in the ID8-VEGF model." (PMID 32756436, 2020). "However, we found that the proportion of CD8+ T cells were significantly decreased despite of increase of DC and CD4+ T cells in tumor after TLR9 agonist stimulation, suggesting that TLR9 agonist may induce immune escape by inhibiting T cell infiltration and activation in tumor microenvironment." (PMID 32483468, 2020). "NETs itself directly upregulates the Toll-like receptor 9 (TLR9) pathways in DLBCL and then NF-κB, STAT3 and p38 pathways promoting tumor progression." (PMID 32731512, 2020). "It has also been demonstrated that the upregulation of TLR9 in glioma cancer stem-like cells is able to activate STAT3 and thus maintain the quiescent state of tumor-repopulating cells." (PMID 32984007, 2020). "Neutrophils can be recruited by CXCL8-secreting tumor cells and, in turn, modulate tumor growth by secreting the proliferation-inducing ligand APRIL and up-regulating the NF-kB, STAT3, and p38 pathways via the Toll-like receptor 9 signal." (PMID 32296632, 2020). "There is evidence that IFN can also repolarize neutrophils and macrophages to an anti-tumor phenotype, which is in agreement with observations made for MDSC in terms of TLR7/8- and TLR9-targeted therapies." (PMID 31694706, 2019). "Like TLR7/8 agonists, TLR9 agonists and STING agonists delivered IT also promote anti-tumor immunity in mouse models, and are currently being investigated in clinical trials (NCT02675439, NCT03172936, NCT02254772)." (PMID 31511088, 2019). "Especially the fact, that the mode-of-action of EnanDIM® molecules via TLR9 starts upstream of the targets of checkpoint inhibitors like anti-PD-1/anti-PD-L1 a combinatory approach may ideally be suited for a synergistic immune activation and thus enhanced anti-tumor effects." (PMID 30621769, 2019). "After 2 days, there were 10 times more FITC+ DCs in the tumor draining lymph nodes of wildtype mice relative to their TLR9−/− counterparts, suggesting that TLR9 signaling is critical for migration of antigen-loaded tumor DCs into regional lymph nodes." (PMID 31619293, 2019). "TLR7/8 agonists (imidazoquinolines), TLR9 agonists (synthetic CpG oligonucleotides) and STING agonists (cyclic di-nucleotides) have all shown potent anti-tumor activity in a range of murine cancer models." (PMID 31511088, 2019). "DaRT used in combination with the TLR9 agonist CpG, or with the TLR1/2 agonist XS15 retarded tumor growth and increased tumor-rejection rates, compared to DaRT alone, curing 41% and 20% of the mice, respectively." (PMID 31637474, 2019). "In this setting, intra-tumoral TLR9 activation cooperated equally with either CTLA-4 or PD-1 blockade co-administered locally or given systemically; however, the uninjected tumor rarely regressed." (PMID 31771649, 2019). "Chemotherapy has also been followed by TLR9 agonist treatment that stimulated DCs maturation and induced CTL response against tumor antigens that had previously been ignored by the immune system." (PMID 31695691, 2019). "A TLR9 agonist combined with chemotherapies and anti-VEGF showed anti-tumor activity in advanced or metastatic lung cancer." (PMID 31547627, 2019). "The mechanism of tumor cell survival, expansion and metastasis is binding to TLR-2, TLR-4, TLR-9 and RAGE, which mediates HMGB1-dependent activation." (PMID 30526680, 2018). "TLR9-agonist SNAs induced potent, TLR9-dependent TH1-type immune responses in mice and monkeys and increased checkpoint inhibitor expression in the tumor." (PMID 30400835, 2018). "TLR9/NF-κB signaling stimulated macrophages to release IL-6, which in turn jump-started proangiogenic and tolerogenic STAT3 signaling leading to tumor recurrence." (PMID 29541413, 2018).
tumor (continued). "Given that BAD-LAMP reduces the capacity of TLR9 to trigger type-I IFN transcription, we hypothesised that a negative amplification loop initiated by TGF-β exposure and by reinforced BAD-LAMP expression could explain partly the dysfunctional status of tumour-associated pDCs." (PMID 29030552, 2017). "The current notion is that CpG-ODNs augment specific immune responses through TLR9 mediated NF-κB activation, as well as CpG-ODN itself exhibits anti-tumour activity via reduction of VEGF and HIF-1α38." (PMID 27558877, 2016). "While TLR9 stimulation increases systemic production of NK and CD8 T cells, local delivery improves tumor infiltration by such cells." (PMID 26343193, 2015). "In vitro studies revealed that activation of TLR9 can mediate oral cancer cell migration by up-regulating MMP2, and tumor cell proliferation by up-regulating cyclin D1 expression, both in an AP-1-dependent manner." (PMID 25999952, 2015). "For the current study, our aim was to test the anti-tumor efficacy of CpG oligodeoxynucleotide (ODN) 1826, a class B toll-like receptor 9 (TLR9) agonist, (henceforth referred to as CpG) in the context of non-myelablative chemotherapy." (PMID 26082836, 2015). "To confirm our observations in TLR9-rich plasmacytoid DCs (pDCs), we adoptively transferred IDG + CpG-pulsed BMDCs and IDG + CpG-pulsed Flt3L-cultured DCs (pDCs) into tumor-bearing mice." (PMID 26215533, 2015). "Immunization with microparticles containing TLR9 and NOD-2 ligands (MIS416) significantly prolonged survival in tumor-bearing mice." (PMID 25888637, 2015). "Especially, TNBC patients that have low tumor TLR9 expression upon diagnosis have a significantly shortened disease-specific survival, as compared with TNBC patients that have high tumor TLR9 expression." (PMID 25101078, 2014). "Further complicating the issue is the fact that specific family members, such as TLR2, TLR4, and TLR9, following detection of corresponding TLR agonists, have a tumor promoting role in the biology of these tumors." (PMID 25411122, 2014). "Comparison of the tumor volume upto day 12 post AIR (as 100% mice were died in AIR cohort by that day) showed significant difference between AIR and AIR+TLR9 agonist group (203±4.7 mm3 vs 85±3.8 mm3 p<0.003)." (PMID 22238604, 2012). "Thus, apart from the direct activation of immune cells, the effect of CpG-ODN stimulation on the secretion of MCP1 by TLR9 expressing tumor cells could possibly lead to anti-tumoral effects due to an increase of local MCP1 production which then might lead to attraction of immune cells." (PMID 15631627, 2005). "A variety of malignant solid tumors and cell lines were tested for TLR9 expression; in addition, we examined direct effects of CpG-ODN upon apoptosis and chemokine production of tumor cells." (PMID 15631627, 2005). "tumours in mice lacking functional CD8 + T cells or TLR9 did not respond to CpG + RT, confirming the dependence on these components for therapeutic efficacy." (PMID 41123840, 2025). "Furthermore, in a preclinical study, an antagonist of TLR9 and TLR7 labeled as HJ901 was investigated and was observed to inhibit tumor cell proliferation in animals and on three of five ABC but not GCB cell lines." (PMID 40437466, 2025). "Additionally, NF-κB activation was elevated in OSCC infiltrative zones, correlating with increased TLR9 and TLR10 expression, reinforcing its role in chronic inflammation and tumour progression." (PMID 40278081, 2025). "In one preclinical study, intratumoral injection of the TLR9 agonist IMO-2125 in combination with systemic anti-PD-1 increased tumor-infiltrating dendritic and T cells in tumor and lymph nodes, resulting in local and distant antitumor effects in a low immunogenic murine PDAC subtype (FC1242)." (PMID 40227779, 2025).
tumor (continued). "DLBCL-derived IL-8 interacted with its receptor (CXCR2) on neutrophils, resulting in the formation of NETs, which directly increased the expression of Toll-like receptor 9 (TLR9) pathways in DLBCL and subsequently activated the NFκB, STAT3 and p38 pathways, promoting tumor progression." (PMID 41019086, 2025). "TLR-9 not only releases PAMPS but also triggers a downstream intracellular cascade, activating NFkB and secreting IFN-1, turning on CD8+ T cells in the tumor microenvironment." (PMID 39202970, 2024). "Furthermore, clinical studies are showing promising effects of TLR9 and TLR7 agonists in enhancing the anti-tumor activity in HNSCC." (PMID 38850110, 2024). "Tumors were also M1-skewed regardless of treatment, so perhaps TLR9 stimulation helped to elevate total circulating M1 macrophage numbers to infiltrate and help redirect tumor-residing M1 macrophages towards a tumor-suppressive phenotype." (PMID 38201300, 2024). "coloaded the hydrophobic chemotherapeutic drug doxorubicin (DTX) and Incorporation of cholesterol‐modified TLR9 agonist in synthetic high‐density lipoprotein cholesterol (HDL) nanodiscs, and found that the use of DTX‐sHDL/CpG inhibited tumor growth and prolonged animal life." (PMID 38685971, 2024). "In addition, many clinical trials (phase I-III) evaluate the activation of pDCs in the tumor using TLR7 and TLR9 agonists—which reactivate their production of type I IFN and cytotoxic molecules (e.g., TRAIL)." (PMID 37190135, 2023). "Tumor-bearing mice were treated intratumorally on days 10 and 16 post-tumor inoculation with ADU-S100, as a STING agonist, and CpG ODN1826, as a TLR9 agonist; both of these are powerful, safe, and effective immunoadjuvants with clinically translational potential." (PMID 37901237, 2023). "Anti-tumor effect of MIP through the TLR2-MyD88 axis has been well elucidated whereas the TLR9- MyD88 axis has not been studied yet." (PMID 37122749, 2023). "TLR9-expressing immune cells were mainly accumulated in the peribronchial capillaries near the tumor, whereas normal mouse lung of same strain and vehicle-treated tissues lacked TLR9-expressing immune cells." (PMID 37435086, 2023). "Additionally, alongside TLR9, TLR7 has been identified as a pivotal regulator in tumor progression and is highly regulated in human HCC tissue." (PMID 37822929, 2023). "In conclusion our work demonstrates the anti-tumor activity of a TLR9 in OS, a high-grade, aggressive tumor for which no targeted therapies or efficient immunotherapies are available." (PMID 37365634, 2023). "In light of the increased expression of PD-1 on tumor-infiltrating CD8 T cells and of PD-L1 on myeloid cells, we tested whether the combination of the TLR9 agonist with systemic administration of anti-PD-1 antibody would increase its therapeutic efficacy." (PMID 37365634, 2023). "The robust upregulation of IFN-β expression in the tumor and spleen tissue, along with the increased infiltration of CD8+ cells and reduced tumor cell mitosis observed in our study, was mainly due to the synergetic effect of STING and TLR9 agonists when administered in combination forms." (PMID 37901237, 2023). "Pre-clinical data suggest that the activation of TLR-9 results in the recruitment of T cells to the tumor microenvironment and can convert non-inflamed tumors to inflamed tumors." (PMID 36831449, 2023). "As TLR9 is mainly expressed by cells of the immune system, we assessed whether SD101 local administration altered the immune tumor microenvironment of both treated and controlater, untreated, lesions." (PMID 37365634, 2023). "Other innovative immunotherapy approaches include using agonists of costimulatory molecules such as 4-1BB, OX40, and TLR9 (NCT02554812), developing personalized tumor antigen-based vaccines (NCT02897765 and NCT03289962), and utilizing cytokine mimetics (NCT03520686 and NCT03625323)." (PMID 37760516, 2023).